IL21 (interleukin 21)
Diseases named in the same sentence as IL21 in open-access papers (continued):
Sharing a sentence is not in itself a finding about the gene and the disease.
lymphopenia (9 papers, 2008 to 2025). Reduction in the number of lymphocytes. "Regarding this, it is possible that IL-2 deficiency, induced by lymphopenia, reduces the expansion and maintenance of Tregs and therefore favors greater proliferation of effector T cells and increasing IL-21 levels." (PMID 39124778, 2024). "The key signal factors IFN-γ (Ifng), IL17a (formally regarded as IL-17), and IL21 were detected by ELISA to assess the influence of activation and lymphopenia of the CD4+ T cells on the inflammatory state." (PMID 40756359, 2025). "Lymphopenia can be promoted by IL-21-induced T cell death through inhibition of IL-7-mediated T cell survival in NOD mice." (PMID 24586733, 2014). "Transient lymphopenia was observed during the IL-21 administration weeks with rapid recovery afterwards, a pattern similar to the observations from IL-21 monotherapy study." (PMID 24829759, 2014). "Improper regulation of T cell homeostatic mechanisms, such as IL-21 inhibition of T cell survival, can result in decreased numbers of lymphocytes, or lymphopenia, as observed in both NOD and C57BL/6 mice compared to IL-21R KO animals of both strains." (PMID 18773086, 2008). "It remains to be seen whether systemic use of other common γ chain cytokines, such as IL-7 or IL-21, could be useful for particular indications (e.g. to counteract lymphopenia)." (PMID 22958464, 2012). "Despite this caveat, our studies in NOD and C57BL/6 mice clearly indicate that IL-21 reduces T cell survival and suggest that it might promote lymphopenia to drive homeostatic proliferation." (PMID 18773086, 2008).
uveitis (9 papers, 2009 to 2022). An inflammatory process affecting a part of or the entire uvea. "In addition, after confirmation of the IL2/IL21 genetic region influence on uveitis genetic predisposition, more studies would be required in order to reveal the causal variant/s responsible and to clear up the influence of this region on the uveitis etiology." (PMID 23676143, 2013). "Functional studies have revealed that Th17 cells contribute to uveitis through expanded IL-2, while IL-21 was highly expressed and promoted the differentiation of Th17 cells in both in vitro and in vivo studies." (PMID 22876110, 2012). "The levels of IL2, IL21, and their receptors were found to be significantly elevated in uveitis patients and animal uveitis models." (PMID 22876110, 2012). "Functional studies have revealed that Th17 cells contribute to uveitis through expanded IL-2, meanwhile IL-21 was highly expressed and promoted the differentiation of Th17 cells both in vitro and in vivo studies." (PMID 22065918, 2011). "Taken together, these studies indicate that IL2, IL21, and IL27 play important roles in the development of uveitis, predicting an association of these two SNPs (rs4505848 and rs4788084) with AU." (PMID 22065918, 2011). "The effectiveness of anti-IL-21/IL-21R or downstream signals in uveitis may be confirmed in future studies." (PMID 33816637, 2021). "Levels of IL2, IL21, and their receptors were significantly increased during uveitis in patients and animal models and they may participate in the regulation of T-cell responses." (PMID 22065918, 2011). "Therefore, we further investigated whether IL-21 could influence the production of IL-17, a vital inflammatory cytokine in the pathogenesis of uveitis." (PMID 20057909, 2009). "They found higher levels of IL-1β, IL-4, IL-17A, IL-17F, IL-21, IL-22, IL-31, IFN-γ, sCD40L, and TNF-α, with a significant difference for IL-17F, in BD-recurrent uveitis patients respect to the BD-remitted uveitis group, before drug infusion." (PMID 31134098, 2019). "The levels of interleukin 2 (IL-2), interleukin 21 (IL-21), and their receptors were found to be upregulated in both experimental autoimmune uveitis (EAU) animals and in uveitis patients." (PMID 22876110, 2012). "Studies have shown that the levels of interleukin 2 (IL-2), interleukin 21 (IL-21) and their receptors were upregulated in both experimental autoimmune uveitis (EAU) animals and in uveitis patients." (PMID 22065918, 2011). "Of note, most of these investigations have compared active with inactive uveitis or a healthy control group showing increased serum levels of different cytokines in the active group, such as the IL-8, IL-6, TNF-α, IL-17, IL-21, IL-23." (PMID 36498608, 2022). "Although there is a distinct relationship between IL-21 and autoimmune uveitis, the biological agents that target IL-21 or IL-21R have not been tested in uveitis." (PMID 33816637, 2021). "Furthermore, IL-21 seems to be involved in the Behçet’s disease (BD) as well as in the Vogt-Koyanagi-Harada (VKH) syndrome pathogenesis, both disorders strongly characterized by the presence of uveitis condition, probably by promoting IL-17 secretion." (PMID 23676143, 2013).
depression (8 papers, 2017 to 2025). "It was found that the level of gene expression for IL-17, IL-21, IL-23, and IL-35 was higher in patients with depression." (PMID 35861930, 2022). "The experiment shows that IL-17, IL-21, IL-23, IL-35 and Foxp3 concentration can be a marker in the diagnosis of depressive disorders." (PMID 33498653, 2021). "In our study we observed that protein expression of IL-21 was significantly higher in the individuals with depression." (PMID 33498653, 2021). "A difference between the mean protein expression of IL-17, IL-21, IL-23, and IL-35 in the group of patients with depression and in the control group was statistically significant." (PMID 33498653, 2021). "However, the mean expression for IL-21, IL-35 and of the Foxp3 gene at mRNA level was significantly reduced in the patients with depressive disorders." (PMID 33498653, 2021). "This could suggest that Th17 cells may exert their effects in depression via cytokines other than IL-17, such as IL-21 and IL-22." (PMID 33935753, 2021). "Additionally, we have demonstrated that T cells from MS patients with major depressive disorder produce more IL-21 compared to those without depression, suggesting a link between IL-21 and neuroinflammation in comorbid conditions." (PMID 40301833, 2025).
helminth infections (8 papers, 2009 to 2024). "Perhaps, IL-21 signaling is a limiting factor for the development of the type 2-associated GC B and Tfh cells during helminth infection." (PMID 33983946, 2021). "IL-4 and IL-21 production by Tfh cells synergistically promotes the GC response during helminth infection." (PMID 33983946, 2021). "Here, we review the roles of IL-21 and its receptor during protozoan and helminth infections in humans and in murine hosts." (PMID 31867283, 2019). "Mice deficient for the IL-21R (Il21r−/−) showed reduced accumulation of immune subsets in the intestine, including lymphocytes, and reduced sizes and numbers of intestinal granuloma following helminth infections, suggesting a critical requirement of the IL-21/IL-21R axis for mounting TH2 responses." (PMID 31867283, 2019). "Mice deficient for a functional IL-21/IL-21R axis failed to elicit anti-helminth-specific IgG1 responses and subsequently were unable to clear helminth infection as compared with their wild-type counterparts." (PMID 31867283, 2019). "To our knowledge, IL25 and IL21 polymorphisms in the Th17 pathway have not been previously associated with worm burden but we have recently hypothesized that they might play a role in worm infection response as they are Th17 pathway genes within SM1 and SM2 loci." (PMID 38033168, 2023).
ischemic stroke (8 papers, 2017 to 2025). A stroke disorder caused by obstruction of blood flow to the brain, due to thrombotic (local blood clot formation) or embolic (due to a blood clot or other material traveling from another site) event. "IL-21 polymorphism is related to the increased susceptibility to ischemic stroke possibly by upregulating gene expression." (PMID 35173738, 2022). "This indicates a higher response can possibly be exerted by IL-21R-expressing neurons in response to IL-21 produced from infiltrated TFH cells during ischemic stroke." (PMID 39472796, 2024). "Previous work shows that a group of CD4+ T cell can produce IL-21 and contributes to damage following transient middle cerebral artery occlusion (tMCAO) in mice and patients with ischemic stroke." (PMID 39472796, 2024). "Total and pJAK3/activated JAK3 and phosphorylated STAT3 levels dramatically increase after ischemic stroke in addition to upregulated IL-21 mRNA." (PMID 28790974, 2017). "Of the six ILs that use the common gamma chain, we identified increased IL-21 expression in the ipsilateral cortex in addition to confirming that our model of ischemic stroke induces significant neuroinflammation with qRT-PCR for several inflammatory mediators." (PMID 28790974, 2017). "Therefore, this study uncovers an important role of CXCL13 expressed on inflamed cerebral vessels in recruiting IL-21-producing TFH cells via CXCR5 to produce neuroinflammation and subsequent neuronal death in ischemic stroke." (PMID 39472796, 2024).
nasal polyps (8 papers, 2014 to 2022). "In the previous study, we found that the levels of IL-21 in nasal polyps (NPs) were significantly increased and associated with polyp size and recurrence." (PMID 26239551, 2015). "In humans, IL-21-producing CD8+ T cells are detected in the tissues of patients with nasal polyps and Hodgkin lymphoma." (PMID 33815416, 2021). "Second, IL-21-producing CD8+ T cells are detected in the tissues of patients with nasal polyps and malignant tumors." (PMID 33815416, 2021). "IL-21-producing CD8 T cells from human nasal polyps co-express IFNγ and IL-21 to induce B cell class-switch to IgG when co-cultured with B cells." (PMID 31275308, 2019). "Recently, also IL-21 and IL-21-producing T follicular helper (Tfh)-like cells were identified as an increased population in nasal polyposis, with the staphylococcal superantigen SEB being one of the triggers for IL-21 expression." (PMID 25379119, 2014). "In nasal polyposis, IL-21 expression was increased after SEB stimulation." (PMID 35878202, 2022). "Our findings here were consistent with our earlier studies in nasal polyps that IL-21 could be produced by CD8+ T cells after PMA plus ionomycin stimulation." (PMID 26785168, 2016). "The authors speculate that T-follicular helper cells and their product, IL-21, are important in the pathophysiology of nasal polyposis by stimulating local immunoglobulin production and germinal center formation." (PMID 25379119, 2014). "In nasal polyposis, SEB can induce IL-21 expression, and IL-21 also induces differentiation of Th17." (PMID 35878202, 2022). "IL-12 enhances IL-21 and IFN-γ production in CD4+ T cells in nasal polyps, especially the percentages of Tfh-like cells." (PMID 26239551, 2015). "Here we sought to quantify IL-17A, IL-17F, IL-21, and IL-22 cytokines produced by Th17 cells in mucosal tissue and peripheral blood of CRSwNP, CRS without nasal polyps (CRSsNP) and control patients." (PMID 29311948, 2017).
Obesity (8 papers, 2018 to 2023). Accumulation of substantial excess body fat. "Many of the common secreted upstream regulators we identified, such as TNF, IL-1β, IFN-γ, IL-18, CD40L, IL-6, EGF, TGFβ, and IL-21, were previously reported to be associated with obesity and metabolic dysfunction." (PMID 36880999, 2023). "Finally, IL-21 has been shown to be increased in adipose tissue during obesity, and IL-21 deficiency leads to the expansion of adipose tissue Treg cells and preserves insulin sensitivity." (PMID 34837070, 2022). "As B cells are involved in the inflammatory landscape present in obesity, undergoing expansion in adipose tissues from mice fed a high‐fat diet, where they can activate T cells and macrophages, they have the potential to receive IL‐21, IFN‐y, and TLR7 stimulation, priming them to a DN2 B‐cell fate." (PMID 37272217, 2023). "Some of these proinflammatory cytokines in obesity include IFN‐y, secreted by CD4+ T cells upon receiving antigen presentation from adipocytes, and IL‐21, which is upregulated in adipose tissues from obese mice." (PMID 37272217, 2023). "Specifically, we observed the levels of IL-1β, IL-6, IL-8, IL-12, IL-17, IL-21, IL-32, and TNF-α were significantly higher in the NAFLD group than in the simple obesity group (all P < 0.001)." (PMID 36530698, 2022). "We found that plasma IL-1β, IL-6, IL-8, IL-12, IL-17, IL-21, IL-32, and TNF-α levels were elevated in obese children with NAFLD compared to subjects with simple obesity." (PMID 36530698, 2022). "The mice lacking IL-21 or mice with specific deletion of STAT3 in T cells fed with HFD showed an increase of VAT Treg cells and an improvement of adipose inflammation and insulin sensitivity, suggesting an important role for IL-21 and STAT3 signaling in regulating VAT Treg cells in obesity." (PMID 30323806, 2018).
atherosclerosis (7 papers, 2014 to 2024). A disease characterized by the build-up of fatty material and calcium deposition in the arterial wall resulting in partial or complete occlusion of the arterial lumen. "IL-21 and IL-21R inhibition has been frequently debated in the literature, where both higher and lower levels have been linked to atherosclerosis." (PMID 27095356, 2016). "In mice with advanced atherosclerosis, Foxp3, Ifng, Il21, and Pdcd1 mRNA levels were increased in the splenic CD3+ cells indicating that atheroprogression drives T-cell activation and regulatory transcriptional programs." (PMID 38270847, 2024). "In atherosclerosis, endothelial dysfunction and vascular inflammation are reversed by lowering IL-21." (PMID 36034959, 2022). "Collectively, it is logical to assume that the cTfh1 cells with nonefficient helper phenotype and cTfh2 and cTfh17 cells with efficient helper phenotype and IL‐21 secretion may be related to atherosclerosis pathogenesis, probably by subset‐specific cytokine production." (PMID 33230950, 2020). "Given that endothelial cells are known to produce MIP-3α, it is possible that IL-21 enhances the migration and accumulation of TH1 and TH17 cells into the vascular wall in both vasculitis and atherosclerosis resulting in inflammation." (PMID 25352848, 2014). "In atherosclerosis, no major studies have been conducted to date to investigate the role of TFH cells, but IL-21 may be involved in tissue damage." (PMID 25352848, 2014).
co-infection (7 papers, 2014 to 2026). "Sustained high CXCL9/CXCL10 in DR-TB may reflect T-cell exhaustion, while IL-21 deficiency in HIV co-infection could impair B-cell responses, promoting immune evasion." (PMID 41007639, 2025). "We found that HCV-specific IL-21 production was enhanced in the PBMC of patients who exhibited relative viral control in acute HIV/HCV coinfection." (PMID 27124305, 2016). "These responses are of interest in HIV/HCV coinfection due to the role of virus-specific IL-21-production in the enhancement of viral clearance and the pro-fibrogenic properties of IL-17A." (PMID 27124305, 2016). "Because IL-21 is not needed for memory inflation following MCMV infection, we asked whether co-infection with MCMV could provide the necessary factors to overcome the inhibition of adenovirus-vaccine-induced memory inflation observed in Il21−/− mice." (PMID 30279090, 2018). "Currently, the impact of IL-21-producing T cells in HIV/HCV coinfection is unclear." (PMID 27124305, 2016). "PBMC from individuals with HIV/HCV coinfection are somewhat refractory to IL-21 treatment." (PMID 27124305, 2016). "This suggests that the presence of HIV coinfection might induce an IL-21 refractory state in the HCV-specific CD8+ T cells of some individuals, as a feature of T cell exhaustion." (PMID 27124305, 2016). "In early HIV/HCV coinfection, IL-21 may contribute to viral control, and may represent a novel tool to enhance acute HCV clearance in HIV/HCV coinfected individuals." (PMID 27124305, 2016). "Together, our findings indicate that IL-21-producing CD4+ T cells are selectively and persistently impaired in the lungs during Mtb/SIV co-infection despite antimicrobial and antiviral therapy." (PMID 42084946, 2026). "Significantly reduced IL-21 and IP-10 levels in HIV/TB co-infection suggest immunosuppression markers, offering new co-infection diagnostic perspectives." (PMID 41007639, 2025). "Our data extend these findings by additionally assessing IL-21 and IL-17 secretion capacity in HIV and MTB co-infection." (PMID 25781898, 2015). "We compared peripheral HCV-specific IL-21 and IL-17A-producing T cell responses with a well-established marker of liver progression, the Fibrotest, as well as LPS levels, a marker of microbial translocation in those with chronic HCV/HIV coinfection." (PMID 27124305, 2016). "Since Th17 cells have the ability to produce both IL-21 and IL-17A, and considering the fact that IL-21 has a known role in viral control, it raises the question of whether these cytokines are produced in an antigen-specific manner in HIV/HCV coinfection." (PMID 27124305, 2016). "This study is the first to investigate the modulation of IL-21 during LTBI and Mycobacterium tuberculosis (Mtb)/ Simian Immunodeficiency Virus (SIV) co-infection in non-human primates (NHP)." (PMID 42084946, 2026).
hepatitis B virus infection (7 papers, 2013 to 2024). A viral infection caused by the hepatitis B virus. "The TFH cell number and/or abnormal function, as well as IL-21 expression deficiency, may be closely associated with the chronicity of hepatitis B virus infection." (PMID 23407366, 2013). "In conclusion, this study suggested that for hepatitis B virus infection, IL-12 and IL-18 rather than IL-21 were more suitable for assessing disease severity of high viral load (5-6log10) patients and IL-21 was more suitable for patients with low viral load (3-4log10)." (PMID 36383803, 2022). "In the present study, serum IL-21 levels were not increased in patients with acute hepatitis B." (PMID 27386263, 2016).
liver disease (7 papers, 2016 to 2025). "Many studies have indicated that the expression of interleukin-21 (IL-21) is associated with the pathogenesis of certain liver diseases." (PMID 28467480, 2017). "The IL‐18 and IL‐21 levels were significantly higher in patients with AIH than in those with other liver diseases and autoimmune disorders." (PMID 37397575, 2023). "Cryptosporidium species was identified in only 2 cases, one of whom had cholangitis and liver disease, which is normally associated with MHC class II or IL-21/IL-21 receptor deficiencies but also described in CD40 ligand and CD40 deficiency." (PMID 27555459, 2017). "IL-21 levels were significantly increased in the serum of patients with AIH compared to those with other liver diseases and controls (p < 0.0001)." (PMID 27386263, 2016). "The main finding of this study was that serum IL-21 levels were significantly increased in the serum of patients with AIH compared to those with other liver diseases and controls." (PMID 27386263, 2016). "Because of the overlap of the liver disease spectrum between the tree shrew and IL-21, it was speculated that promoting tree shrews as ideal animal models would be very valuable." (PMID 28467480, 2017). "Additionally, the in vivo study of IL-21-related liver diseases has been conducted in a transgenic mouse model, but the occurrence and development of human liver diseases, particularly hepatitis virus infection, could not be fully mimicked." (PMID 28467480, 2017). "However, in alternative animal models of liver diseases, it remains unknown whether the tree shrew could be utilized to analyze the relationship between IL-21 and liver diseases." (PMID 28467480, 2017). "In light of the pivotal role of immune parameters (e.g., CXCL13, IL21, IL6, and CCL20) in the distinct microbial composition at early liver disease stages and in general with cognitive impairment, we determined which specific bacterial taxa are related to these patterns." (PMID 41035890, 2025).